CCNB1 (cyclin B1)
Diseases named in the same sentence as CCNB1 in open-access papers (continued):
Sharing a sentence is not in itself a finding about the gene and the disease.
tumor (continued). "In the Hh signaling pathway, PTCH1 is regarded as the primary regulator, and it modulates the intracellular localization of Cyclin B1, thereby linking its tumor-suppressive role to the regulation of cellular division." (PMID 40170839, 2025). "Beyond this well-known role, the CCNB1/CDK1 complex also influences tumor-related signaling pathways." (PMID 40430484, 2025). "IHC analysis of tissue microarray revealed elevated CCNB1 expression in tumor tissues in comparison to adjacent normal tissues, with higher expression levels significantly associated with advanced pathological grade." (PMID 40682115, 2025). "Further investigations reveal that Halorotetin B binding to UBE2C induced M phase cell cycle arrest by inhibiting the ubiquitin-mediated degradation of key cell cycle regulators, including cyclin B1 and securin, ultimately leading to tumor cell senescence." (PMID 41387196, 2025). "Tumor volume measurements revealed that SNRPB overexpression promoted tumor growth, while CCNB1 knockdown significantly inhibited tumor growth." (PMID 40682115, 2025). "The combined treatment group showed an intermediate tumor weight, suggesting that CCNB1 knockdown partly mitigates the tumor-promoting effect of SNRPB overexpression." (PMID 40682115, 2025). "Numerous studies have shown that aberrant expression of CCNB1 plays a critical role in accelerating cell cycle progression, thereby promoting uncontrolled cell proliferation and rapid tumor growth, as well as contributing to therapeutic resistance." (PMID 40567110, 2025). "This modification process is essential for enhancing Cyclin B1 expression and promoting the G2/M transition process during tumor growth." (PMID 40723282, 2025). "Lactate-induced metabolic reprogramming promoted cell cycle progression through upregulation of cell cycle protein B1 (CCNB1), which further enhanced tumor drug resistance." (PMID 40166469, 2025). "To further evaluate the SNRPB/CCNB1 axis in vivo, we established subcutaneous xenograft tumor models." (PMID 40682115, 2025). "Second, the anti-tumor effects of CCNB1/CDK1 inhibition extend beyond PD-L1 regulation, including modulation of the IL-6-JAK-STAT3 axis and TGF-β signaling." (PMID 40430484, 2025). "Another study showed that CREPT interacts with Aurora B kinase, which accelerates the upregulation of Cyclin B1 and increases the G2/M transition, contributing to cancer cell proliferation and tumor growth." (PMID 40723282, 2025). "Seven genes were associated with recurrence and progression: ADAMTS6, CRMP1, PTTG, ASK, CCNB1, AURKB, and CENPE, while ADAMTS6, CRMP1, ASK, CCNB1, and CENPE were also associated with tumor recurrence and progression." (PMID 41303810, 2025). "Substantial evidence confirms elevated CCNB1 expression across tumor types enhances malignant proliferation and metastasis." (PMID 41614789, 2025). "Further analysis of the MMH cohort revealed that a high or low expression (transcript levels lower or higher than the cohort median) of KPNA2/FOXM1/CCNB1/CCNB2 is associated with ER, PR, HER2, and Ki67 status, molecular subtype, tumor grade, and AJCC stage." (PMID 40002266, 2025). "This change upregulated CCNB1 transcription, promoted cell cycle progression, and enhanced the resistance of tumor cells to pemetrexed." (PMID 40166469, 2025). "Based on the discovery of the CCNB1 expression levels in different tumor clinico-pathological stages, we further assessed the relationship between CCNB1 expression and patient prognosis across various cancers, using Cox regression and Kaplan–Meier analyses." (PMID 38581717, 2024). "In conclusion, our survival analysis reveals that tumor stage and molecular markers such as CCNB1 expression are critical prognostic factors in this cohort of patients." (PMID 39795587, 2024). "The aim of this study is to evaluate the relative changes in the expression levels of CDC20 and CCNB1 genes among tumor grades and cancer stages in patients with BC." (PMID 39795587, 2024).
tumor (continued). "We also obtained immunohistochemical images from the HPA database to assess CCNB1 protein expression in tumor samples." (PMID 38581717, 2024). "The expressions of miR-4516 were lower, while the expressions of Wnt 8B, DVL3, FOSL1, CDK1, CDK2, CCNA1, and CCNB1 were enhanced in tumor tissue compared to normal lung tissue in the human samples." (PMID 38930863, 2024). "Due to the significance of cell division and the cell cycle for tumor development, CCNB1 is crucial for tumor development." (PMID 38609711, 2024). "Cyclin B1 as a marker of cell cycle activation decreased in tumor tissues across all patients and timepoints with a few exceptions." (PMID 38672538, 2024). "It was observed that dietary methionine dramatically expedited heterotopic ESCC tumor growth in a dose-dependent manner, accompanied by enhanced intratumoral expression of cyclin B1 and PCNA." (PMID 38570607, 2024). "CCNB1 is a key molecule in the G2-M phase transition during the cell cycle and is overexpressed in various tumor types." (PMID 39795587, 2024). "Our findings suggest that the dysregulation of CCNB1 is involved in tumor progression across multiple cancer types." (PMID 38581717, 2024). "Significant expression differences of CCNB1 and BCL-2 were observed in 501 PCa tissue samples compared to 52 non-tumor tissue samples, with PCa tissues exhibiting significantly higher expression of CCNB1 and lower expression of BCL-2." (PMID 39318781, 2024). "Specifically, we seek to understand the connection between CDC20 and CCNB1 and higher tumor grade and cancer stage." (PMID 39795587, 2024). "For example, one study used WGCNA on normal and tumor tissue, identifying a module enriched in metabolic and cell cycle pathways, with CCNB1 emerging as a significant hub gene—similar to our findings." (PMID 39452074, 2024). "As a member of the cyclin family, CCNB1 is highly expressed in a variety of human tumor tissues and is closely related to tumor cell proliferation, metastasis, and poor prognosis in patients." (PMID 38816744, 2024). "CCNB1 is expressed in tumor samples at a significantly higher rate than in their adjacent normal samples (p = 1.565 × 10−49)." (PMID 38254834, 2024). "CCNB1 plays a crucial role in tumor immunology and holds significant prognostic value, presenting potential as a new biomarker for both prognosis and immunotherapy across various cancers." (PMID 38581717, 2024). "Correlation analysis indicated a positive relationship between CDC20 expression and tumor grade (r = 0.284, p = 0.038) and between CCNB1 expression and tumor stage (r = 0.301, p = 0.027)." (PMID 39795587, 2024). "Overexpression of CCNB1, CCNB2, DLGAP5, and ASPM is associated with tumor progression and poor prognosis." (PMID 39045407, 2024). "The abnormal CCNB1 expression is not only affecting tumor cell proliferation but also apoptosis, migration, and invasion." (PMID 38581717, 2024). "CCNB1 expression demonstrated a significant positive correlation with tumor stage, suggesting its role in promoting tumor invasiveness and progression." (PMID 39795587, 2024). "In summary, the deregulation of CCNB1 plays a key role in neoplastic transformation and drives the proliferation of tumor cells." (PMID 39795587, 2024). "MET was enriched in proliferating tumor cells featuring high levels of markers of cell cycle progression such as cyclins b1 and b2 (CCNB1, CCNB2), proliferating-cell nuclear antigen (PCNA) and Ki67 (MKI67) and likely define yet another subset of MBM." (PMID 38386085, 2024). "The results confirmed that a significant downregulation of cyclin B1, cyclin D1, and cyclin E1 in four tumor cell lines were stimulated with H9." (PMID 39458945, 2024). "Meanwhile, the deletion of Cyclin B1 has been shown to inhibit tumor cell proliferation and decrease apoptosis." (PMID 38611876, 2024).
tumor (continued). "As a key regulator of the G2/M transition in the cell cycle, elevated CCNB1 expression likely reflects increased proliferative activity in advanced tumor stages." (PMID 39795587, 2024). "We checked the expression levels of CCNB1, which is one of the upregulated OncotypeDX genes in tumor samples, versus adjacent normal samples (from paired DEA)." (PMID 38254834, 2024). "Previous research has demonstrated that CCNB1 plays a crucial role in mediating cell cycle progression by reprogramming energy metabolism in tumor adaptive resistance." (PMID 38233752, 2024). "The mRNA and protein levels of cyclin A2 and cyclin B1 were increased in a tumor compared to normal samples and are promising biomarkers for the diagnosis and prognosis for CRC-suffering patients." (PMID 37316878, 2023). "The KEGG analysis of intersecting genes indicated that CCNB1 was mainly involved in the “cell cycle” in tumor pathogenesis." (PMID 37758792, 2023). "Gene expression, tumor stage, survival status, immune infiltration and other factors were included in the analysis to explore the potential molecular mechanism of CCNB1 in different cancers." (PMID 37758792, 2023). "To investigate the effect of FYLM on tumor growth, we detected the levels of cell proliferation, cell cycle, and apoptosis-related protein Ki-67, cyclin B1, Bcl-2 and cleaved Caspase-3 in xenograft mouse tumor tissues by western blot and immunohistochemistry." (PMID 36744262, 2023). "The expression levels of ACADL, ACADS, ACADSB, ALDH6A1, ETFDH, and GCDH were found to be lower in tumor samples compared to normal samples, whereas the expression levels of CCNB1 and CDK1 were observed to be higher in tumor than in normal samples." (PMID 37994323, 2023). "We explored the potential mechanism of CCNB1 in tumors through the tumor microenvironment (TME) and DNA methylation." (PMID 37758792, 2023). "Further exploration led to the identification and validation of CDK1, CCNB1, AURKA, EZH2, and CCNA2, a five-gene signature with high interactions and potentially associated with tumor stemness, hypoxia enhancement, and TME regulation." (PMID 37189841, 2023). "We show here that cyclin B1 is differentially modulated among tumor (strongly downregulated) and normal (mildly downregulated) breast epithelial cells." (PMID 37888205, 2023). "There was a significant increase in tumor markers (SCCAg and CCNB1) among workers whose BPDE-Alb adduct ≥ 15 ng/ml." (PMID 36287252, 2023). "In conclusion, our study indicated that the expression of CCNB1 is widely increased in many tumor types, and the expression is positively correlated with the poor prognosis of patients." (PMID 37758792, 2023). "A high CCNB1 protein level was significantly correlated with high tumour grade (including high pleomorphism scores, high mitotic count scores), poor NPI, hormonal receptor negativity (ER/PR) (all p < 0.0001) and HER2 positivity (p = 0.011)." (PMID 36418517, 2023). "CCNB1 is also involved in the proliferation, migration, apoptosis, chemoresistance and metastasis of tumours." (PMID 36418517, 2023). "High CCNB1 mRNA expression was associated with aggressive tumour behaviour, including LVI, larger size, higher tumour grade, high lymph nodal stage, hormonal receptor negativity, HER2 positivity and poor clinical outcome (all p < 0.0001)." (PMID 36418517, 2023). "Deregulation of cyclin B1 is involved in tumor transformation and promotes cancer cell proliferation." (PMID 37759511, 2023). "High expression of CCNB1 mRNA in both the METABRIC and TCGA cohorts showed an association with large tumour size, high tumour grade, poor NPI, LN stage, LVI positivity, ER−, PR− and HER2+." (PMID 36418517, 2023).
tumor (continued). "Our results in head and neck PDX tumor tissue indicate a positive correlation between the levels of cyclin B1 protein and apoptosis induced upon DMA treatment." (PMID 36230831, 2022). "Unlike Bas BCs, and similar to UroA tumors, UroB mostly show the organization of a basal cell layer, as well as a gradient of proliferation, as confirmed by a polarization of CCNB1 positive cells perpendicular to the tumor-stroma interface." (PMID 35887192, 2022). "In tumor cells, the formation and activation of the CCNB1-Cdk1 complex initiates steps in mitosis, including condensation of chromosomes, assembly of spindle poles and breakdown of the nuclear envelope." (PMID 35731831, 2022). "As transcription factors, FOXM1 can regulate downstream cell cycle-related genes, including PLK, cyclin B1, cyclin D1, and Cdk2, to promote cell proliferation and tumor progression." (PMID 36585925, 2022). "Recent results suggest that circ-CCNB1 is a powerful circular RNA in the inhibition of tumor progression." (PMID 35731831, 2022). "It is conceivable that a high frequency of cycling tumour cells in a biopsy taken early in treatment, using, for example, Cyclin B1 as a marker, would predict an increased likelihood of resistance acquisition through this mechanism." (PMID 36267209, 2022). "More and more evidence suggest that cyclin B1 is highly expressed in several tumors, and its effects were correlated with tumor proliferation, invasion, and apoptosis." (PMID 35629160, 2022). "In tumor cells, circ-CCNB1 has been shown to bind to both CCNB1 and CDK1, thereby inhibiting the formation of the CCNB1-CDK1 complex and its entry into the nucleus, resulting in the inhibition of tumor growth and extension of mouse viability." (PMID 35731831, 2022). "Expression of CCNB1 is significantly elevated in samples from LUAD patients and is associated with advanced tumor stage and shorter OS, and TTK is a mitotic checkpoint kinase that is present in higher amounts in some human cancers than in normal tissue." (PMID 35860256, 2022). "The crosstalk between CCNB1 and tumor infiltrating immune cells in BC indicates that CCNB1 is a potential target for future treatment of BC, although no further relationship can be established in the current study." (PMID 36040381, 2022). "After correlation analysis, expression analysis, and survival analysis of miR-139-5p, miR-139-5p was confirmed to be the most plausible upstream tumor suppressive miRNA of CCNB1." (PMID 36040381, 2022). "CDK1/CCNB1 were crucial cell cycle proteins, regulating mitochondrial bioenergetics in cell cycle progression and tumor resistance." (PMID 35155425, 2022). "FOXM1 is essential for progression to the DNA replication and mitosis stages and stimulates the proliferation of tumour cells during the progression of NSCLC via the Cyclin B1." (PMID 35410446, 2022). "For further analysis, the GlioVis database showed increased mRNA expression levels of CCNB1/CDC42/MAPK7/CD44 oncogenes in GBM tissues compared to non-tumor tissues." (PMID 35008426, 2022). "Eventually, the upregulation of CCNB1 in BC tumor tissues was confirmed by immunohistochemistry in the Human Protein Atlas (THPA) database." (PMID 36040381, 2022).
tumor (continued). "It has been reported that cyclin B1/CDK1-mediated mitochondrial bioenergetics plays a role in tumor cell survival and the reduction in anticancer efficacy." (PMID 35681641, 2022). "The methylation levels of CCNB1 were lower in tumor tissues than in normal tissues and were negatively correlated with gene expression." (PMID 33996604, 2021). "Cyclin B1 is involved in neoplastic transformation and, thus, promotes the proliferation of tumor cells." (PMID 34944868, 2021). "Silencing hsa_circ_0035483 increases gemcitabine sensitivity and inhibits tumour growth via regulation of miR‐335/CCNB1 axis." (PMID 34672397, 2021). "Western blot analysis revealed that expression of cell cycle regulatory factors Cyclin B1 and Cdk1 in tumor tissue decreased significantly in response to treatment with PP*-P8." (PMID 34039418, 2021). "Abnormal expression of the CCNB1 gene can influence the cell cycle and cell proliferation, leading to various malignant tumours." (PMID 34603487, 2021). "Further survival analyses, ROC curve analysis and representative image analysis, selected 5 hub genes, including CDK1, CDC20, CCNB1, CENPF, and MAD2L1, that were associated with early diagnosis, tumour stage, and poor outcomes of HCC." (PMID 34603487, 2021). "MiR-379 expression showed positive correlation with increasing tumor stage and expression of Cyclin B1." (PMID 34575183, 2021). "There are also reports that cyclin B1 expression decreased when G2/M phase arrest was induced in tumor cells." (PMID 34916946, 2021). "Western blotting indicated the augmentation of cleaved PARP and cyclin B1 and downregulation of cyclin D1, suggesting that heptelidic acid exerted tumor-suppressive functions by mediating the dysregulation of the cell cycle and induction of apoptosis." (PMID 34040123, 2021). "CCNB1 has a function in controlling the cell cycle at the G2/M phase, and its overexpression promotes cell proliferation, tumour growth and cancer recurrence." (PMID 34366863, 2021). "Meanwhile, the expression of CCNA2 and CCNB1 was positively correlated with tumor-killing immune cells, such as CD8+ T cells.The copy numbers of CCNA2, CCNB1, CCND1, CCNE1, and CCNF was positively related to gene expression." (PMID 33996604, 2021). "The CDK1/cyclin B1 complex not only mediates mitochondrial activities during cell cycle progression but also plays a critical role in tumor adaptive resistance." (PMID 33744866, 2021). "CircCcnb1 dissociates the Ccnb1–Cdk1 complex and forms a large ternary complex of circCcnb1–Ccnb1–Cdk1, inhibiting tumor growth and extending survival." (PMID 34449657, 2021). "CCNB1 is a key molecule that regulates G2/M phase progression and can affect tumour growth and metastasis." (PMID 34244479, 2021). "Further, ISL1 enhanced tumor growth and targeted the downstream genes CCNB1, CCNB2, and C-myc in GC." (PMID 33962568, 2021). "Nuclear miR-373 and miR-744 can bind the CDH1 (E-cadherin) and CCNB1 (cyclin B1) promoters, respectively, to induce expression and modulate tumor growth." (PMID 34199614, 2021). "The arrest of cells in G2/M phase was accompanied by a reduced level of CDK1 and cyclin B1, suggesting that the mechanism of tumour growth inhibition was mediated through reduced CDK1/cyclin B1 activity." (PMID 34503199, 2021). "Depletion of cyclin B1 also contributed to the similar effects in various kinds of tumor cells, including HeLa, MCF‐7, and PC‐3." (PMID 34231329, 2021). "Upregulated CCNB1 in NSCLC closely correlates with tumor growth, differentiation, and vascular invasion." (PMID 34359836, 2021).